SRY (sex determining region Y)
Diseases named in the same sentence as SRY in open-access papers (continued):
Sharing a sentence is not in itself a finding about the gene and the disease.
disorders of sex development (5 papers, 2010 to 2023). "46,XY female disorders of sex development (DSDs) with SRY mutations, historically known as Swyer syndrome, involve congenital incomplete or disordered gonadal development in which there is discordance between genetic, gonadal and phenotypic characteristics." (PMID 36694125, 2023). "Approximately 10–15% of 46,XY disorders of sex development (DSDs) have an SRY mutation residing in the high mobility group (HMG) domain." (PMID 36694125, 2023). "In dogs, with 7 copies of the SRY gene, reduced SRY CN is thought to be associated with an increased risk of disorders of sex development (DSD)." (PMID 36227030, 2022). "SRY mutations causing disorders of sex development (DSD), including gonadal dysgenesis and hermaphroditism, have been reported at 25 positions within HMG domain." (PMID 29338681, 2018). "This is the second report that describes the mosaic fertile father who shows milder features associated with testicular dysgenesis syndrome and third report that describes the patients with sex development disorders (DSD) having mosaic mutation in SRY gene." (PMID 20849656, 2010). "The present and the previous published paper strengthens the role various genetic factors along with the underlying mutations in SRY gene play in abnormal sex development disorders, related to malignant transformation of germ cells." (PMID 20849656, 2010). "In human embryogenesis, loss of SRY (sex determining region on Y), SOX9 (SRY-related HMG box 9) or SF1 (steroidogenic factor 1) function causes disorders of sex development (DSD)." (PMID 21412441, 2011).
Klinefelter syndrome (5 papers, 2006 to 2023). A sex chromosome disorder caused by the presence of an extra X chromosome in the male karyotype. "The patient was diagnosed with nonmosaic 47, XXY Klinefelter Syndrome with the AZF deletion absent and SRY+." (PMID 26843994, 2015).
Parkinson disease (5 papers, 2017 to 2022). A progressive degenerative disorder of the central nervous system characterized by loss of dopamine producing neurons in the substantia nigra and the presence of Lewy bodies in the substantia nigra and locus coeruleus. "Another study has also found that SRY expression in human cell cultures and rats can be linked to Parkinson’s disease." (PMID 35794589, 2022). "In Parkinson’s disease, the expression of Y chromosome gene, SRY, is upregulated and promotes nigrostriatal degeneration." (PMID 33927243, 2021). "In midbrain dopamine neurons, SRY positively regulates catecholamine synthesis and metabolism, possibly explaining male bias in fight-flight behaviours and “dopamine disorders”, such as Parkinson’s disease and schizophrenia." (PMID 35794589, 2022). "Indeed, human SRY is expressed in both the postnatal ENS and midbrain-associated dopaminergic neurons, and antisense oligonucleotide-mediated knockdown of Sry is neuroprotective in experimental Parkinson’s disease in rats." (PMID 32898154, 2020). "For example, expression of the sex-determining region Y (SRY) gene is elevated in dopamine neurons in human and experimental Parkinson’s disease models and suppression of its expression could exert protective functions against the disease in these models." (PMID 32817785, 2020).
androgen insensitivity syndrome (4 papers, 2010 to 2020). Androgen insensitivity syndrome (AIS) is a disorder of sex development (DSD) characterized by the presence of female external genitalia, ambiguous genitalia or variable defects in virilization in a 46,XY individual with absent or partial responsiveness to age-appropriate levels of androgens. "This revealed a novel and likely pathogenic missense variant (p.Arg130Pro, c.389G>C) in SRY, one of the major genes implicated in complete gonadal dysgenesis, hence securing this condition over androgen insensitivity syndrome as the cause of the patient’s disorder of sexual development." (PMID 27821113, 2016). "As the chromosomal sex identified as male with the corresponding 64, XY karyotype with the presence of SRY gene, a 64, XY DSD syndrome and Androgen Insensitivity Syndrome was suspected, leading to the molecular testing of the AR-gene." (PMID 31936796, 2020).
Frasier syndrome (4 papers, 2008 to 2024). Frasier syndrome is characterized by the association of male pseudohermaphrodism and glomerular nephropathy. "If WT1−KTS is upregulated, such as in Frasier syndrome, WT1−KTS antagonizes SRY expression, resulting in pre-granulosa cell differentiation and male-to-female sex reversal in mice." (PMID 39359415, 2024).
hypospadias (4 papers, 2012 to 2022). Hypospadias is the displacement of the urethral meatus on the ventrum of the penis. "He showed signs associated with TDS; hypospadias, cryptorchidism, a testicular GCC (seminoma) and oligoasthenozoospermia, suggesting that mutations in SRY may be associated with TDS." (PMID 23157850, 2012). "However, the lack of SROs found on the Y chromosome support more recent research that has found no CNVs on this chromosome, including SRY, in patients with isolated hypospadias." (PMID 35457073, 2022).
Primary amenorrhea (4 papers, 2010 to 2023). "Among the 15 adolescents with primary amenorrhea and low testosterone concentration, we identified two new SRY mutations, five new SF1 mutations and one new LH receptor gene mutation." (PMID 20302644, 2010). "Our study confirms the 10-15% prevalence of SRY mutations and shows the high prevalence (33%) of SF1 abnormalities in primary amenorrhea due to 46,XY DSD with low plasma testosterone concentration." (PMID 20302644, 2010). "A hemizygous c.230_231insA mutation in SRY was identified in a female patient with 46,XY complete gonadal dysgenesis (DSD01), and a heterozygous c.7389delA mutation in CHD7 was found in a woman with a small uterus, primary amenorrhea, short stature, and dysplastic ears (DSD04)." (PMID 26980296, 2016). "We directly sequenced SRY, SF1 and WT1 genes in 15 adolescent girls with primary amenorrhea, low testosterone concentration, and XY karyotype, to determine the prevalence of mutations." (PMID 20302644, 2010). "As expected, hemizygous variants in SRY were found in three women with CGD who had presented with absent puberty and primary amenorrhea in adolescence." (PMID 31745530, 2019). "To conclude, the genetic analysis of low-testosterone primary amenorrhea due to 46,XY DSD is complex since several factors may be involved, including SRY, SF1, WT1 and LH receptor." (PMID 20302644, 2010). "We specifically focused on SRY, SF1 and WT1 because these genes have previously been reported to be implicated in adolescents presenting with primary amenorrhea due to 46,XY DSD in association with low pl-T, but no other signs." (PMID 20302644, 2010).
anorchia (3 papers, 2011 to 2020). "We evaluated the clinical and biological presentation, and family histories of 26 boys with anorchia, and sequenced their SRY, NR5A1, INSL3, MAMLD1 genes and the T222P variant for LGR8." (PMID 21853106, 2011). "All patients with anorchia were sequenced for SRY, NR5A1, INSL3, MAMLD1 and the T222P variant of LGR8 and no pathogenic mutations were identified." (PMID 27899089, 2016).
gastric cancer (3 papers, 2017 to 2020). A primary or metastatic malignant neoplasm involving the stomach. "The human sex determining region Y (SRY)–related high-mobility-group (HMG) box protein family member 17 (SOX17) protein also binds to the KL promoter in gastric cancer cells, thereby inducing KL expression." (PMID 33520985, 2020).
germ cell tumor (3 papers, 2010 to 2023). A benign or malignant, gonadal or extragonadal neoplasm that originates from germ cells. "Here, we present a case of 46,XY DSD caused by a novel missense mutation in the HMG region of SRY rapidly progressing to germ cell tumors (GCTs)." (PMID 36694125, 2023). "Presence of the SRY gene in females results in XY sex reversal and increased risk of gonadal germ cell tumours if the karyotype also includes the so-called GonadoBlastoma on the Y chromosome (GBY) region." (PMID 20849656, 2010). "It is of importance to note that mosaic patients without a SRY mutation also have a risk for malignant germ cell tumors." (PMID 20849656, 2010).
Hypertension (3 papers, 2015 to 2017). The presence of chronic increased pressure in the systemic arterial system. "The analyses of SHR-specific genes using IPA revealed that B-cell CLL/lymphoma 6 (Bcl6) and SRY (sex determining region Y)-box 2 (Sox2) were possible candidate genes responsible for causing hypertension in SHRs." (PMID 26165378, 2015). "The IPA path explorer tool revealed that B-cell CLL/lymphoma 6 (Bcl6) and SRY (sex determining region Y)-box 2 (Sox2) were possible candidate genes that trigger hypertension in SHRs." (PMID 26165378, 2015). "In light of preliminary data for the overexpression of human SRY within the rat kidney, this suggests a high probability of SRY involvement in blood pressure regulation and potentially hypertension, with the rat serving to provide mechanistic understanding of SRY within the kidney." (PMID 26848384, 2016).
osteosarcoma (3 papers, 2019 to 2025). A usually aggressive malignant bone-forming mesenchymal neoplasm, predominantly affecting adolescents and young adults. "Wnt1 overexpression is regulated by SRY (Sex-determining Region Y)-Box (SOX9) in osteosarcoma." (PMID 39926108, 2025). "Similarly, melatonin strongly suppresses the migration and invasion of stem cells by a potent suppression of SRY (sex determining region Y)-box (SOX9) in an in vivo model of osteosarcoma." (PMID 38473317, 2024).
Hepatic fibrosis (2 papers, 2022 to 2023). The presence of excessive fibrous connective tissue in the liver. "Another study revealed that overexpression of lncRNA-H19 downregulated the expression of ZEB1 (E-box-binding homeobox 1) and upregulated expression of EpCAM (epithelial cell adhesion molecule) and SRY (sex determining region Y)-box 9 in a mouse model of cholestatic liver fibrosis." (PMID 37919785, 2023).
mantle cell lymphoma (2 papers, 2010 to 2018). Mantle cell lymphoma is a rare form of malignant non-Hodgkin lymphoma affecting B lymphocytes in the lymph nodes in a region called the ``mantle zone''. "Expression of SRY [sex-determining region Y]-box11 (SOX11) is specific to mantle cell lymphoma (MCL) and contributes, in conjunction with immunoglobulin variable heavy chain gene mutation status, to the identification of two forms of this disease." (PMID 29484276, 2018). "The SRY (sex determining region Y)-box 11 (SOX11) transcription factor was recently discovered as a new marker in mantle cell lymphoma (MCL), expressed in both cyclin D1 positive and negative cases." (PMID 21124928, 2010).
neuroblastoma (2 papers, 2017 to 2023). Neuroblastoma (NB) is the most common solid, extracranial childhood tumor. "Suppression of SRY in human neuroblastoma cell line, M17, results in a depressed expression of TH, DOPA decarboxylase (DDC), dopamine β-hydroxylase (DBH), and monoamine oxidase A (MAO A) expression." (PMID 29200993, 2017).
osteoporosis (2 papers, 2019 to 2021). A condition of reduced bone mass, with decreased cortical thickness and a decrease in the number and size of the trabeculae of cancellous bone (but normal chemical composition), resulting in increased fracture incidence. "SRY contributes to the sex disparity observed in osteoporosis, downregulating expression of nuclear factor κB ligand (RANKL), known also to promote invasiveness of glioblastoma cells." (PMID 33807423, 2021). "SRY shows promise as an osteoporosis marker in men, or for development of treatment for both genders." (PMID 31409771, 2019). "We hypothesized that SRY-mediated RANKL gene expression might be the molecular mechanism underlying the sex differences in bone metabolism and bone diseases, such as osteoporosis." (PMID 31409771, 2019). "Our results indicate that SRY could be one of the reasons for gender differences in bone mineral density and for gender differences in the pathogenesis of osteoporosis." (PMID 31409771, 2019). "Moreover, our data suggest that SRY is one of the regulators of RANKL expression in males and might protect men from osteoporosis." (PMID 31409771, 2019).
preeclampsia (2 papers, 2015 to 2020). Preeclampsia is a hypertensive disorder of pregnancy that is characterized by new-onset hypertension with proteinuria presenting after 20 weeks of gestation, and depending on mild or severe forms may initially present with severe headache, visual disturbances, and hyperreflexia. "We compared the concentrations of DSCR3, RASSF1A, and SRY as cell-free fetal DNA markers in 188 normal pregnancies, 16 pregnancies with early-onset preeclampsia (EO-PE), 47 pregnancies with late-onset preeclampsia (LO-PE), and 29 pregnancies with gestational hypertension (GH)." (PMID 26694356, 2015).
21 hydroxylase deficiency (1 paper, 2012). "Also, we were unable to find a known etiology for the existence of a female pseudohermaphroditism as there was no history of hormonal intake, and the genetic tests for the SRY translocation and 21 hydroxylase deficiency were negative." (PMID 22811944, 2012).
Adrenal insufficiency (1 paper, 2013). Insufficient production of steroid hormones (primarily cortisol) by the adrenal glands. "Complete sex reversal in 46,XY males without adrenal insufficiency can also occur in conditions such as Leydig cell hypoplasia or due to mutations in SRY, DHH, SOX9, DMRT1, WNT1, or ATRX." (PMID 23748066, 2013).
amenorrhea (1 paper, 2010). The absence of menses in a woman who has achieved reproductive age. "Among the genetic causes of low-testosterone primary amenorrhea due to 46,XY DSD, SRY gene is reported to be frequently involved, but other genes, such as SF1 and WT1, have never been studied for their prevalence." (PMID 20302644, 2010).
Anophthalmia (1 paper, 2021). Absence of the globe or eyeball. "Mutations in SRY (sex determining region Y)-box2 (SOX2) account for approximately 20% of human anophthalmia cases." (PMID 33494192, 2021).
autism (1 paper, 2018). Persistent deficits in social interaction and communication and interaction as well as a markedly restricted repertoire of activity and interest as well as repetitive patterns of behavior. "In particular, we highlight the emerging role of the Y-chromosome gene, SRY, in the male brain and its potential role as a male-specific risk factor for disorders such as PD, autism, and ADHD in many individuals." (PMID 30104506, 2018). "The Y-chromosome gene, SRY, which directly exerts male-specific actions in adult dopamine neurons, may also underlie male preponderance to disorders such as PD and autism." (PMID 30104506, 2018). "Moreover, emerging evidence from animal models and clinical observations also suggest a role for targeting X-linked (e.g., steroid sulfatase) or-Y-linked (SRY, neuroligin-4) genes for male-biased neurodevelopmental disorders such as autism or ADHD." (PMID 30104506, 2018). "Given that SRY is expressed in brain regions closely associated with pathophysiology of ADHD and autism, abnormal regulation of SRY expression during development, and consequently dopamine machinery genes, may contribute to the hyper- or hypo-function of dopamine levels in these disorders." (PMID 30104506, 2018).
autoimmune disease (1 paper, 2020). A disorder resulting from loss of function or tissue destruction of an organ or multiple organs, arising from humoral or cellular immune responses of the individual to their own tissue constituents. "Meanwhile, SRY has been shown to have a strong relationship with autoimmune diseases." (PMID 32721949, 2020).
breast carcinoma (1 paper, 2020). "IKKβ targeting reduces breast cancer mammosphere formation and tumourigenicity, and positively regulates Lin28B and SRY (sex determining region Y)-box 2 (SOX2) to promote breast cancer stemness and reduces breast GD2+ TICs, thereby reducing metastasis." (PMID 32823550, 2020).
cognitive disorder (1 paper, 2017). A disease affects cognitive processes. "SRY effects on MAOA and RET expression could affect normal synaptogenesis and neurotransmission, and enteric nervous system development, and contribute to pathogeneses of diseases associated with these two genes, i.e. depression/cognitive disorders and Hirschsprung disease respectively." (PMID 28646221, 2017).
Crohn disease (1 paper, 2024). A gastrointestinal disorder characterized by chronic inflammation involving all layers of the intestinal wall, noncaseating granulomas affecting the intestinal wall and regional lymph nodes, and transmural fibrosis. "A similar approach has been used to introduce large deletions in the porcine SRY gene for study causes of sex reversal in gene-edited pigs and a 93-bp deletion in the 3ʹ-untranslated region (UTR) of the TNFα gene to generate a porcine Crohn’s disease model." (PMID 39684387, 2024).
de la Chapelle syndrome (1 paper, 2021). "We are hereby reporting a rare case of de la Chapelle syndrome (SRY negative)." (PMID 33628654, 2021).
embryonal carcinoma (1 paper, 2011). A non-seminomatous malignant germ cell tumor characterized by the presence of large germ cells with abundant cytoplasm resembling epithelial cells, geographic necrosis, high mitotic activity, and pseudoglandular and pseudopapillary structures formation. "We demonstrate that endogenous SOX9 is upregulated in the human embryonal carcinoma cell line NT2/D1 over-expressing SRY, a model of presumptive Sertoli cells." (PMID 21412441, 2011). "To test whether human SRY can activate SOX9 transcription we evaluated the human embryonal carcinoma cell line, NT2/D1, as a model of presumptive Sertoli cells." (PMID 21412441, 2011).
gonadal agenesis (1 paper, 2024). A congenital disorder characterized by the complete absence of gonadal tissue. "Among the known genes associated with nonsyndromic 46, XY gonadal agenesis, variants of SRY, NR5A1, and MAP3K1 are the most common." (PMID 38915825, 2024).
hepatoblastoma (1 paper, 2021). Hepatoblastoma (HB) is a malignant hepatic tumor and is the most common pediatric liver cancer. "miR-126 downregulation notably attenuated hepatoblastoma tumor growth and decreased the ratio of CD44+ CD90+ CD133+ cells and increased the expression of IL-6, Oct4, SRY, TGF-β, and β-catenin in tumor tissues of mice." (PMID 34746322, 2021). "EVs derived from hepatoblastoma cells significantly increased the ratio of CD44+ CD90+ CD133+ cells and increased the expression of IL-6, Oct4, SRY, and TGF-β in bone marrow mesenchymal stem cells (BMSCs), while EVs with downregulated miR-126 reversed these phenomena." (PMID 34746322, 2021).
leukemia (1 paper, 2018). A malignant (clonal) hematologic disorder, involving hematopoietic stem cells and characterized by the presence of primitive or atypical myeloid or lymphoid cells in the bone marrow and the blood. "For example, GATA1 partners with HNF1 in hematopoietic progenitor cells; with PPARA:RXRA in leukemia; with SRF, CDX and FOXP3 in primary T-cells; with SRY, NKX2-1, FOXF1, OCT4 and ZBTB16 in differentiated ESCs and with TAL1:TCF3 motif co-occurring in various fibroblasts." (PMID 30142147, 2018).
medulloblastoma (1 paper, 2012). A malignant, invasive embryonal neoplasm arising from the cerebellum. "Inhibition of PLK1 impaired tumor sphere formation of medulloblastoma cells and decreased the expression of SRY (sex determining region Y)-box 2 (SOX2) mRNA in tumor spheres indicating a possible role in targeting tumor inititiating cells." (PMID 22390279, 2012).
Micropenis (1 paper, 2025). "This study confirmed that SRY-negative cases have more severe genital abnormalities: with the most common EMS is 3 < EMS ≤ 6, only four cases presented with isolated micropenis without other external genital abnormalities, the age at initial diagnosis was very young." (PMID 40487758, 2025).